H19 (H19 imprinted maternally expressed transcript)
Diseases named in the same sentence as H19 in open-access papers (continued):
Sharing a sentence is not in itself a finding about the gene and the disease.
esophageal squamous cell carcinoma (6 papers, 2016 to 2025). Esophageal squamous cell carcinoma (ESCC) is a type of esophageal carcinoma (EC) that can affect any part of the esophagus, but is usually located in the upper or middle third. "Recently H19 has been demonstrated to be up-regulated in esophageal squamous cell carcinoma (ESCC) and shown to be the precursor of miR-675 that encodes miR-675-5p conservatively." (PMID 27120794, 2016). "Alternatively, in esophageal squamous cell carcinoma, H19 CTCF-binding site 6 (CBS6) hyper-methylation correlates with overexpression of IGF2 in patients." (PMID 35459174, 2022). "Increased H19 expression promoted the epithelial–mesenchymal transition, growth, and invasion of ESCC (esophageal squamous cell carcinoma) and NPC by inhibiting E-cadherin expression and modulating the STAT3/EZH2/β-catenin pathway." (PMID 41020820, 2025).
Glucose intolerance (6 papers, 2015 to 2024). Glucose intolerance (GI) can be defined as dysglycemia that comprises both prediabetes and diabetes. "In this context, increased expression of H19 in the liver of diabetic mice is associated with increased HGP and glucose intolerance." (PMID 34298896, 2021). "This is primarily due to abnormal methylation of the H19-Igf2 locus, which further induces transgenerational glucose intolerance and abnormal insulin levels." (PMID 28814771, 2017).
keloid (6 papers, 2018 to 2025). An irregularly shaped, elevated mark on the skin caused by deposits of excessive amounts of collagen during wound healing. "H19 expression was increased in keloid tissue and fibroblasts, whereas miR-196b-5p expression was decreased." (PMID 36046343, 2022). "H19 expression was upregulated in human keloids compared with normal scars and normal skin controls." (PMID 36046343, 2022). "Recent evidence has shown that H19 is related to enhanced proliferation activity of keloid fibroblasts." (PMID 30458806, 2018). "H19 is also found to enhance proliferation ability of keloid fibroblasts through the regulation of mammalian target of rapamycin (mTOR) and vascular endothelial growth factor." (PMID 30458806, 2018). "Verification of the molecular and cellular mechanisms of H19 in fibrotic diseases may contribute to the development of novel therapeutic approaches for fibrotic diseases including keloid." (PMID 36046343, 2022). "A recent study also showed that H19 expression was markedly increased in keloid tissues and HKFs." (PMID 36046343, 2022). "In summary, H19 might may be an active mode in keloid formation and serve as a potential therapeutic target for keloid patients." (PMID 36046343, 2022). "Therefore, H19 promotes keloid progression via sponging miR-196b-5p and increasing SMAD5 expression." (PMID 36046343, 2022). "Recently, H19 has also been observed to be upregulated in keloid tissues and fibroblasts." (PMID 33520460, 2021). "In summary, H19 might be a potential marker of keloid diagnosis or treatment." (PMID 36046343, 2022). "The in vitro assay showed that lncRNA H19 might facilitate proliferation and metastasis of fibroblasts by modifying downstream miR-29a and COL1A1, engaging in the development of keloid-targeted treatments." (PMID 33243301, 2020). "Its upregulation in keloid tissue enhances cell growth and angiogenic activity, whereas H19 knockdown suppresses proliferation and downregulates mTOR and VEGF expression, identifying H19 as a key pro-fibrotic regulator and potential therapeutic target in keloid pathogenesis." (PMID 41424791, 2025).
mastitis (6 papers, 2017 to 2025). Inflammation of breast tissue during lactation or postpartum due to an obstructed duct or infection. "The results suggest that H19 mediates mastitis-caused mammary fibrosis." (PMID 29062612, 2017). "However, the role of H19 in bovine mastitis and mastitis-caused fibrosis is still unclear." (PMID 29062612, 2017). "We further detected H19 expression in inflammatory MAC-T cells in an epithelial cell model of mastitis by treating MAC-T cells with LPS or LTA according to the concentration recommended in our previous publication." (PMID 29062612, 2017). "We found that H19 was highly expressed in bovine mastitis tissues and inflammatory MAC-T cells induced by virulence factors of pathogens." (PMID 29062612, 2017). "We first observed that the expression level of H19 was upregulated in both mastitic mammary tissue compared to normal tissue, indicating that H19 is involved in the immune response of mammary glands during bovine mastitis." (PMID 29062612, 2017). "We hypothesized that H19 upregulation is involved in mammary fibrosis induced by mastitis." (PMID 29062612, 2017). "In a bovine model of mastitis (a system with noted differences from human PCM), H19 modulates both TGF-β1-induced EMT and the production of ECM components through the PI3K/Akt signaling cascade, thereby promoting the formation of mammary fibrotic tissue." (PMID 41019090, 2025). "In a cell model of bovine S. aureus mastitis, lncRNA-TUB and H19 mediated Escherichia coli-induced inflammatory factor secretion and S. aureus adhesion to epithelial cells." (PMID 36418939, 2022). "In the cell model of bovine S. aureus mastitis, the S. aureus adhesion to epithelial cells can be mediated by lncRNAs TUB and H19, and the NF-κB/NLRP3 inflammasome pathway is regulated by the lncRNA XIST." (PMID 34895356, 2021). "In addition, our results clearly demonstrate the molecular mechanism of H19 as responsive to TGF-β1 and that EMT occurs in vivo during bovine mastitis." (PMID 29062612, 2017).
metastatic tumor (6 papers, 2007 to 2023). "Our clinical data identify H19 as a candidate diagnostic marker and predictive marker of NEPC with elevated H19 levels associated with an increased probability of biochemical recurrence and metastatic disease in patients receiving ADT." (PMID 34934057, 2021). "Furthermore, in the first report on the importance of the Twist gene product in tumor metastasis, the investigators showed that H19 is the highest differentially expressed gene in metastatic tumor cell lines investigated." (PMID 17786216, 2007). "Furthermore, the expression level of H19 in metastatic tumor is significantly higher than in non-metastatic tumor." (PMID 33123473, 2020).
oral cancer (6 papers, 2021 to 2025). "We demonstrated that lncRNA H19 knockdown in oral CAFs not only attenuated glycolysis and affected cellular biological behaviors but also suppressed tumor progression in oral cancer." (PMID 33762576, 2021). "Intriguingly, through RT-PCR, we found that lncRNA H19 in several oral cancer cell lines, including Cal-27, UMSCC-1, HSC-2 and FaDu cells, was significantly increased compared to the level in normal oral keratinocytes (NOKs)." (PMID 33762576, 2021). "To further address the functional impact of lncRNA H19 in oral cancer, we used a CCK-8 array and found that lncRNA H19 knockdown inhibited the proliferation of oral CAFs." (PMID 33762576, 2021). "LncRNA H19 was identified as a key lncRNA in oral CAFs and was synchronously upregulated in both oral cancer cell lines and CAFs." (PMID 33762576, 2021). "H19 is abnormally expressed in oral cancer and plays a role as a “sponge molecule”." (PMID 36035993, 2022). "In addition to H19, there are many lncRNAs that aggravate the development of oral cancer by promoting the migration and invasion of cancer cells, such as lncRNA FGD5-AS1, lncRNA MYOSLID, and lncRNA HOTAIR." (PMID 36035993, 2022). "Given that the expression levels of H19 and miR-29b were found to be significantly higher and lower in oral cancer tissues, respectively, we sought to investigate whether H19 interacts with miR-29b and regulates the precancerous development of oral cancer." (PMID 33672311, 2021). "In this study, by performing in vitro and in vivo experiments, we targeted lncRNA H19 as a potential EMCT and highlight its potential value in the development of a therapeutic approach for oral cancer." (PMID 33762576, 2021).
renal carcinoma (6 papers, 2019 to 2025). A carcinoma arising from the epithelium of the renal parenchyma or the renal pelvis. "Notably, HIF-2α silencing was capable of rescuing H19 transcript upon combined treatment in the HIF-2α+ VHL-deficient renal carcinomas cellular context." (PMID 31426484, 2019). "Among all the lncRNA candidates predicted by the BiGAN as being associated with renal cancer, 7 lncRNAs were among the top 10 in the predicted list, (MALAT1 1st, HOTAIR 2nd, PVT1 3rd, NBAT1 4th, UCA1 5th, H19 6th, and MEG3 7th)." (PMID 34193046, 2021). "The higher expression of H19 is found in renal cancer cells compared to the nonmalignant renal cells HK-2." (PMID 34983363, 2022). "To confirm the selective involvement of HIF-2α, but not that of HIF-1α, in the H19 downregulation, we evaluated changes in the H19 response to combined treatment in the VHL-deficient renal carcinomas cells (786-O) that express endogenous HIF-2α, but not HIF-1α." (PMID 31426484, 2019).
rhabdomyosarcoma (6 papers, 2014 to 2026). A rare aggressive malignant mesenchymal neoplasm arising from skeletal muscle. "Of note, rhabdomyosarcomas are associated with genetic alterations in a specific chromosomal region (11p15) that harbors a cluster of imprinted genes, including H19." (PMID 41521159, 2026). "Rhabdomyosarcoma cells show a loss of imprinting due to aberrant methylation in this region, resulting in increased expression of IGF2 and downregulation of H19 and its growth‐suppressing miRNAs." (PMID 41521159, 2026). "The aberrant methylation and subsequent loss of heterozygosity in this region can lead to the inactivation of H19, contributing to rhabdomyosarcoma development." (PMID 41521159, 2026). "ERH also interacts with the H19 gene and regulates growth in nephroblasts, rhabdomyosarcomas and choriocarcinoma cells." (PMID 30866868, 2019).
tongue squamous cell carcinoma (6 papers, 2019 to 2024). A squamous cell carcinoma that arises from the tongue. "Through its sponging function, H19 also facilitates the migration and invasion of tongue squamous cell carcinoma cells by suppressing let-7a, leading to the activation of its target gene HMGA2, which, in turn, promotes EMT." (PMID 34572067, 2021). "For instance, lncRNA H19 contributes to progression of tongue squamous cell carcinoma through interaction with EZH2." (PMID 33292221, 2020). "In tongue squamous cell carcinoma (TSCC), the long noncoding RNA (lncRNA) H19, by binding to (sponging) let-7a to inhibit its function in repressing let-7 target gene HMGA2, facilitates TSCC cell migration and invasion." (PMID 34572067, 2021). "A very recent study also showed that the expression level of H19 was higher in patients with metastasized (vs non-metastasized) tongue squamous cell carcinoma, and was higher in tumor cells than normal squamous cells." (PMID 32024523, 2020).
aortic aneurysm (5 papers, 2019 to 2025). A ruptured aneurysm located in the wall of the proximal portion of the descending aorta proceeding from the arch of the aorta. "While H19 expression decreases in the ECs of aging mice, increased H19 expression in SMCs induces aortic aneurysms in animal models." (PMID 35130955, 2022). "Many studies have identified H19 as a biomarker or driver of other cardiovascular diseases such as aortic aneurysm, smooth muscle cell apoptosis, endothelial cell aging, and ischemic heart failure." (PMID 31609547, 2019).
autism (5 papers, 2015 to 2025). Persistent deficits in social interaction and communication and interaction as well as a markedly restricted repertoire of activity and interest as well as repetitive patterns of behavior. "In a similar way, the lncRNA H19 was found to be increased in autism and to compete with the action of miR-484, which was downregulated in autistic probands." (PMID 40868063, 2025). "Also, the imprinted gene Dio3 in male pups, while H19 and Xist in female pups, were upregulated by high gestational folic acid supplementation, accompanied by different expressional changes in the candidate autism susceptible gene Auts2 between male and female pups." (PMID 36386900, 2022).
benign breast disease (5 papers, 2021 to 2023). "For example, compared to benign breast disease (BBD) and healthy controls, serum exosomal H19 was significantly increased in BC patients, and high serum exosomal H19 expression was strongly associated with worse clinical variables." (PMID 35150011, 2022).
brain injury (5 papers, 2019 to 2024). Acute and chronic (see also brain INJURIES, CHRONIC) injuries to the brain, including the cerebral hemispheres, CEREBELLUM, and brain STEM. "This study demonstrates that the identified H19-miR-19a-Id2 axis plays a critical role in hypoxia induced neuronal apoptosis, and blocking this axis may serve as a novel therapeutic strategy for ischemic brain injury." (PMID 31170091, 2019).
diabetic retinopathy (5 papers, 2019 to 2025). "In diabetic retinopathy, the long noncoding RNA H19 inhibits the endothelial-mesenchymal transition." (PMID 35599572, 2022). "Additionally, EndMT was regulated by H19 during diabetic retinopathy where overexpression of H19 prevented glucose mediated EndMT through regulation of TGF-β1 signaling in a Smad-independent manner." (PMID 31681761, 2019).
infarction (5 papers, 2019 to 2024). A localised pathological necrosis of tissue resulting from obstruction of the blood supply usually by a thrombus, an embolus, or vascular torsion. "The lncRNA H19 (H19) and lncRNA myocardial infarction-associated transcript (MIAT) which are mainly expressed in the heart." (PMID 37525174, 2023). "Here, we investigated the role of H19 after infarction and explored its interacting proteins, particularly those responses to cardiac remodeling and fibrosis." (PMID 31588235, 2019).
leiomyoma (5 papers, 2019 to 2025). A well-circumscribed benign smooth muscle neoplasm characterized by the presence of spindle cells with cigar-shaped nuclei, interlacing fascicles, and a whorled pattern. "The abnormally high expression of H19 in fibroids may influence the expression of fibroid-promoting genes and stimulate the proliferation of leiomyoma cells, which could be the mechanism underlying H19 involvement in UFs." (PMID 37507391, 2023). "Consistent with previous reports, we observed an increase in H19 expression in leiomyoma tissue samples relative to myometrium." (PMID 32094355, 2020). "Recent work suggests that DNA methylation in leiomyomas is mediated by the long non-coding RNA H19, which regulates TET3 expression." (PMID 32094355, 2020). "In this report we show that H19 expression is significantly increased in fibroids as compared with normal myometrium, and that H19 functions to promote leiomyoma cell proliferation and expression of MED12, HMGA2, TET3, and ECM-remodeling genes." (PMID 31089260, 2019). "According to our previous findings, H19 expression was shown to be much higher in UFs than in the normal myometrium; H19 stimulated leiomyoma cell proliferation as well as the expression of MED12, HMGA2, ten-eleven translocation 3 (TET3), and ECM remodeling genes." (PMID 37507391, 2023). "Thus, we concluded that in primary leiomyoma cells H19 promotes HMGA2 expression at the translational level by reducing the bioavailability of let-7." (PMID 31089260, 2019). "As HMGA2 is among the key driver genes in leiomyomas, we tested whether H19 regulates its expression in leiomyoma cells." (PMID 31089260, 2019). "Both H19 and TET1, a key regulator of DNA methylation, were identified to be strong predictive markers for postoperative recurrence of fibroids, suggesting that levels of H19 and TET1 could potentially be used as diagnostic/predictive markers." (PMID 40862769, 2025). "The results showed that LINC02433, LINC01449, SNHG12, H19, and HOTTIP were elevated in premenopausal fibroids, but remained unchanged in postmenopausal ones, while ZEB2-AS1 displayed higher levels only in postmenopausal fibroids." (PMID 40862769, 2025). "When H19 was downregulated, cell viability decreased without affecting apoptosis, suggesting that H19 positively affects leiomyoma cell proliferation." (PMID 31089260, 2019).
macrosomia (5 papers, 2016 to 2026). "Further studies confirmed a strong association between IGF2/H19 methylation and intrauterine hyperglycemia-induced macrosomia." (PMID 36902459, 2023). "We also provided the evidence of strong associations between methylation of IGF2/H19 DMRs and macrosomia induced by intrauterine hyperglycemia." (PMID 26840070, 2016). "In addition, we explored the independent association between IGF2 gene expression and macrosomia by comparing the expression levels of IGF2 mRNA/H19 RNA in maternal peripheral blood and fetal cord blood of humans." (PMID 37152930, 2023). "Here we hypothesize that alteration in methylation at differentially methylated region of the insulin-like growth factor 2 and H19 is associated with macrosomia induced by intrauterine hyperglycemia." (PMID 26840070, 2016). "The gene expression of IGF2 and H19 in cord blood may be associated with macrosomia." (PMID 26840070, 2016). "The present study also explored the independent association between the IGF2 gene and macrosomia by detecting and comparing the expression levels of IGF2 mRNA/H19 RNA in maternal peripheral blood and fetal cord blood of 26 human pregnancies." (PMID 37152930, 2023). "On the other hand, a following study observed that the macrosomia induced by intrauterine hyperglycemia was strongly associated with the cord blood methylation and placenta gene expression status of IGF2/H19." (PMID 37107594, 2023). "Compared with that in the fetal cord blood of the normal birth weight group (CTRL-F), the mRNA expression of IGF2 in the fetal cord blood of the macrosomia group (MF) was increased, and the RNA expression of H19 was significantly reduced." (PMID 37152930, 2023). "The mRNA expression of IGF2 showed significant decrease and the H19 RNA showed higher expression in the maternal peripheral blood of the macrosomia group (MM), compared with that in the normal birth weight group (CTRL-M)." (PMID 37152930, 2023). "In order to observe the associations between methylation of IGF2/H19 DMRs and macrosomia induced by intrauterine hyperglycemia, we analyzed the methylation levels of IGF2/H19 DMRs of umbilical cord blood of neonates born to normal and GDM." (PMID 26840070, 2016). "In addition, we found an independent correlation between IGF2 levels and macrosomia by comparing the expression levels of IGF2/H19 in maternal peripheral blood and fetal cord blood." (PMID 37152930, 2023). "Our previous studies also indicated that a high glucose concentration in the context of GDM increased the expression of IGF2 and its imprinted gene (H19) by changing the levels of methylation in the IGF2 and H19 gene promoters, which might be the underlying pathogenic mechanism of macrosomia." (PMID 37152930, 2023).
ovarian tumor (5 papers, 2009 to 2018). "H19 is a paternally imprinted, oncofetal gene expressed in various embryonic tissues and in 85% of the ovarian tumors." (PMID 28154921, 2017). "We developed a new therapeutic strategy to target expression of the diphtheria toxin fragment A gene in ovarian tumor cells under the control of H19 regulatory sequences." (PMID 20663201, 2010). "Hence, we developed a new therapy strategy to target the expression of diphtheria toxin gene under the control of H19 regulatory sequences in ovarian tumor cells." (PMID 19656414, 2009).